VCP (valosin containing protein)
Diseases named in the same sentence as VCP in open-access papers (continued):
Sharing a sentence is not in itself a finding about the gene and the disease.
cardiomyopathy (12 papers, 2016 to 2023). A disease of the heart muscle or myocardium proper. "For example, cardiac-restricted VCP loss-of-function has been found to disrupt myofibrillar organization, cause aggregation of myocardial ribosomal proteins, and induce cardiomyopathy." (PMID 35743185, 2022). "Missense mutations in the VCP gene have been associated with clinical variability, including myopathy and cardiomyopathy." (PMID 33567613, 2021). "Mice that overexpress mutant VCP/p97 (VCP/p97 K524A) are prone to cardiomyopathy under cardiac pressure overload due to loss of ATPase activity." (PMID 33439255, 2021). "In addition, knockdown of TER94, the Drosophila ortholog for p97/VCP, perturbs myofibril organization and function in Drosophila hearts, and causes cardiomyopathies." (PMID 33467597, 2021). "Interestingly, expression of three MSP-associated disease alleles also disrupted the Drosophila heart and influenced its performance, consistent with cardiomyopathy observed in humans with analogous VCP mutations." (PMID 27500162, 2016). "Cardiac-specific overexpression of an enzymatically mutated VCP (VCPK524A) in transgenic mice resulted in an impairment of the ATPase activity within the D2 domain of VCP, and lead to the development of cardiomyopathy." (PMID 32481679, 2020). "BD cytoplasmic inclusion bodies of heart muscle cells in the majority of elderly individuals are different from other cardiomyopathies including those with inclusions containing mutant proteins such as desmin or valosin-containing protein." (PMID 30413735, 2018). "The potential for cardiomyopathy and heart failure underscores critical roles for VCP in cardiac muscle, which are likely perturbed during disease." (PMID 27500162, 2016). "DN-VCP confers a functional inhibition of VCP in the heart through competitively interfering EN-VCP’s ATPase activity and unbalancing the VCP’s co-factors interaction and nuclear translocation, leading to cardiomyopathy and dysfunction during the aging transition." (PMID 34831118, 2021). "Finally, it is important to design and develop VCP inhibitors for the treatment of various cancers, and activators of VCP to restore the VCP in stressed hearts, to prevent cardiomyopathy." (PMID 32481679, 2020). "In addition, experiments on transgenic mice revealed that disruption of VCP activity could lead to the development of cardiomyopathy and defects in cardiomyocyte nuclear morphology, which suggests the pleiotropic functions of VCP in cardiac homeostasis." (PMID 35369356, 2022). "The prevalence of cardiomyopathy among patients with VCP MSP is unknown but appears to be rare." (PMID 35093159, 2022). "With this unique mouse model, our study provides novel evidence for the role of VCP function in the heart at a non-stressed state and the potential mechanisms associated with the development of cardiomyopathy and cardiac dysfunction induced by impaired VCP function." (PMID 34831118, 2021). "However, despite these significant findings, the role of VCP in the pathogenesis of cardiomyopathy, and the mechanisms involved, remain largely unknown." (PMID 32481679, 2020). "Thus, future studies, including such screens, may identify genetic modifiers of VCP-induced cardiomyopathy and therapeutic targets to alleviate the pathophysiological remodeling of the heart that is associated with MSP." (PMID 27500162, 2016). "The role of VCP in the pathogenesis of cardiomyopathy has been studied with a mutant VCP-overexpressing mouse model lacking adenosine triphosphatase activity, which resulted in the development of cardiomyopathy." (PMID 33567613, 2021).
inclusion body myositis (12 papers, 2014 to 2025). A slowly progressive degenerative inflammatory disorder of skeletal muscles characterized by late onset weakness of specific muscles and distinctive histopathological features. "Finally, we studied myoblasts from patients with muscular disorders characterised by protein aggregates resembling those found in ALS, such as a sporadic Inclusion Body Myositis (IBM) and a vacuolar myopathy related to Valosin-Containing Protein (VCP) mutations (devoid of ALS/FTD manifestations)." (PMID 39283487, 2024). "The titin-binding pattern of chaperones was regularly observed in Duchenne muscular dystrophy (DMD), LGMD2A, MFM-filaminopathy, MFM-myotilinopathy, titinopathy, and inclusion body myopathy due to mutations in valosin-containing protein, but not in acquired sporadic inclusion body myositis." (PMID 28915917, 2017). "Similar to VCP, mutations in p62 can either lead to distinct clinical phenotypes or result in a multisystem proteinopathy with coexisting signs of ALS/FTD, PDB and inclusion body myositis (IBM)." (PMID 40395983, 2025). "In addition, TDP-43-positive inclusions have also been described in the skeletal muscles of the patients with sporadic inclusion body myositis (sIBM) and in IBM with mutations in the valosin-containing protein (VCP)." (PMID 30837838, 2019). "However, myopathy is the most common presentation of VCP-MSP and it is possible that some cases of VCP-MSP are misdiagnosed as sporadic inclusion body myositis based on reactivity to NT5C1A antibodies." (PMID 35741724, 2022).
lung carcinoma (11 papers, 2011 to 2024). "Furthermore, high expressions of MEST and VCP were associated with poor survival of lung cancer patients." (PMID 34560900, 2021). "We measured the expressions of MEST and VCP by performing IHC of tissue microarrays containing 90 and 87 pairs of primary lung cancer tissues and adjacent normal tissues, respectively." (PMID 34560900, 2021). "The interaction between MEST and VCP was then confirmed by both immunoprecipitation and immunofluorescence staining analysis, showing that MEST co-localized with VCP in the perinuclear area of lung cancer cells." (PMID 34560900, 2021). "Other authors showed that the VCP/p97 gene is a target of miR-129 and is downregulated in human lung cancer, thus suggesting that miR-129 is a tumor suppressor miRNA that plays an essential role in the development and progression of this cancer." (PMID 34576340, 2021). "A positive correlation with statistical significance (P = 0.033) was found between MEST and VCP expression, highlighting a critical role of these two proteins in lung cancer progression." (PMID 34560900, 2021). "We report the discovery that MEST regulates lung cancer metastasis by activating the VCP/NF-κB/MMP2 signaling pathway." (PMID 34560900, 2021). "Collectively, these results demonstrate that MEST plays an important role in driving invasion and metastasis of lung cancer by interacting with VCP to coordinate the IκBα/NF-κB pathway." (PMID 34560900, 2021). "VCP has also been previously identified as a potential biomarker for predicting the success of platinum-based chemotherapy in lung cancer patients." (PMID 32404140, 2020). "In this study, we observed a reduction of VCP in either miR-129 overexpressing or hypomethylated lung cancer cells, and verified that VCP gene is a target of miR-129." (PMID 26081366, 2015). "VCP-Expression was described as a suitable marker for prediction of grade of metastasis and prognosis in esophageal, gastric, prostate and lung carcinoma." (PMID 25463965, 2014). "Collectively, these results indicate that MEST and VCP could be prognostic biomarkers for patients with lung cancer." (PMID 34560900, 2021). "Furthermore, analyzing the expression of MEST and VCP by using the Gene Expression Omnibus database, we found that the expression levels of these genes in lung cancer tissues were markedly higher than in normal tissues." (PMID 34560900, 2021). "Targeting the MEST/VCP/IκBα/NF-κB signaling pathway may be a promising strategy to treat lung cancer." (PMID 34560900, 2021). "In addition, our study highlights the value of considering both MEST and VCP expression levels for lung cancer prognosis, as evidenced by the correlation of their levels with lung cancer N-stage and patient survival." (PMID 34560900, 2021). "Whether VCP plays key roles in the cellular functions of miR-129 in lung cancer still needs to be further investigated." (PMID 26081366, 2015). "It is speculated that miR-339-5p inhibits the VCP expression to inhibit the metastasis of lung cancer, but the exact mechanism is unclear." (PMID 25009651, 2014). "Furthermore, we find that the VCP locus is lost in nearly 50% of lung adenocarcinoma patients, suggesting that VCP function may be critical in lung cancer progression." (PMID 25970786, 2015). "Furthermore, recent work from the Vij group demonstrated that sustained inhibition of VCP may be a viable target for killing lung cancer cells." (PMID 25970786, 2015). "VCP is a multifunctional protein, and it has been shown to interact with MEST, promoting invasion and metastasis in lung cancer." (PMID 38495507, 2024). "Another two tissue microarrays consisting of 30 primary lung cancer tissues and matched metastatic tissues were further used to determine MEST and VCP expression, respectively." (PMID 34560900, 2021). "Therefore, MEST and VCP may be useful prognostic biomarkers and drug targets for lung cancer." (PMID 34560900, 2021).
lung carcinoma (continued). "By performing IP assay in lung cancer cells, we found that MEST bound to the C-terminal domain of VCP, suggesting that MEST may be a cofactor by binding to the C-terminal domain of VCP." (PMID 34560900, 2021). "Elevated VCP expression has also been found to correlate with the progression and clinical prognosis of non-small cell lung carcinoma (NSCLC), which accounts for roughly 85% of all cases of lung cancer." (PMID 22216170, 2011).
motor neuron disease (11 papers, 2012 to 2025). "Mutations in the VCP gene are associated with multisystem proteinopathies, a disease spectrum that includes myopathies, bone diseases, neurodegenerative diseases, and motor neuron diseases." (PMID 40969353, 2025). "The diagnosis of patients with mutations in the VCP gene can be complicated due to their broad phenotypic spectrum including myopathy, motor neuron disease and peripheral neuropathy." (PMID 37603075, 2023). "MATR3-related pathology, encompassing myopathy and motor neuron disease, represents an illustrative example of multisystem proteinopathy (MSP), such as other diseases associated to mutations in VCP, HNRNPA2B1, HNRNPA1, and SQSTM1 genes." (PMID 34659085, 2021). "Despite the involvement of VCP mutations in multiple neurodegenerative conditions including motor neuron disease, a systemic evaluation of the role of VCP in axonal transport in an in vivo system is currently lacking." (PMID 32373611, 2020).
ovarian carcinoma (11 papers, 2012 to 2023). A malignant neoplasm originating from the surface ovarian epithelium. "In a cell line model where both VCP alleles are wild-type, for example in OVSAHO ovarian cancer cells, resistant cells harbor two distinct de novo mutations in the corresponding VCP alleles." (PMID 31358864, 2019). "We observed acquired mutations in VCP in ovarian cancer cells upon the acquisition of in vitro resistance to CB-5083." (PMID 29367883, 2017). "In addition, this study reported an association between low VCP expression and poor response to platinum-based chemotherapy in multiple ovarian cancer cohorts." (PMID 32404140, 2020). "In human choriocarcinoma, NSCLC, and ovarian cancer, VCP inhibition resulted in G0/G1 cell cycle arrest." (PMID 36923647, 2023). "In ovarian cancer, it was discovered that inhibition of the therapeutic target valosin-containing protein (VCP) enhances P-eIF2α and ATF4 expression." (PMID 37601686, 2023). "The results demonstrated VCP as a common essential gene across the cancer cell lines with strong genetic dependency towards ovarian cancer cell lines." (PMID 35740614, 2022). "Here, we show that a clinically achievable dose of mifepristone is synergistic with VCP inhibition in ovarian cancer cells." (PMID 35740614, 2022). "Through this study, we identified strong synergistic cytotoxicity between mifepristone and several classes of VCP inhibitors at a clinically achievable dose of mifepristone in ovarian cancer cells." (PMID 35740614, 2022). "In our current study, we investigated the in vitro efficacy of CB-5083 in ovarian cancer and identified new strategies to enhance the cytotoxic effect of VCP inhibitors in combination with other compounds that modulate the unfolded protein response." (PMID 35740614, 2022). "Our results indicate that VCP inhibitors can be combined with other endoplasmic reticulum stress-inducing agents to produce synergistic cytotoxicity in ovarian cancer cells." (PMID 35740614, 2022). "Consistent with this idea, the analysis of VCP knockout effects in ovarian cancer cells from the Dependency Map project indicates CCNE1-amplified cells, such as COV318, ONCODG1, OVCAR3, and SNU8, show strong dependency on VCP." (PMID 35740614, 2022). "Our results show that VCP inhibitors can be combined with other ER stress inducers or UPR modulators to produce synergistic cytotoxicity in ovarian cancer cells." (PMID 35740614, 2022). "Previously, we reported that inhibition of growth arrest and DNA damage-inducible 34 (GADD34) by salubrinal results in synergistic cytotoxicity with VCP inhibitors, including CB-5083, in several ovarian cancer cell lines." (PMID 35740614, 2022). "Serum VCP/p97 levels were measured in ovarian carcinoma, non-Hodgkin’s lymphoma and breast, colon, pancreatic, lung and prostate cancer patients." (PMID 35158912, 2022). "Another study also identified VCP as one of the essential genes in cyclin E1 (CCNE1) amplified ovarian cancer cells." (PMID 35740614, 2022). "Previously, we showed that the unfolded protein response pathway can be induced in ovarian cancer by inhibiting VCP." (PMID 35740614, 2022). "In the case of ovarian cancer specifically, VCP has been found to be an essential gene in cell lineages, and a study showed that ovarian cancer was sensitive to VCP inhibition." (PMID 35841038, 2022). "Here, we show that VCP inhibitors induce cytotoxicity in several ovarian cancer cell lines and these compounds act synergistically with mifepristone, a drug previously shown to induce an atypical unfolded protein response." (PMID 35740614, 2022). "In alignment with these findings, VCP has been investigated as a drug target for ovarian cancer therapy." (PMID 32404140, 2020). "VCP is an ovarian cancer-specific essential gene as demonstrated by a pooled short hairpin RNA (shRNA) screen in 25 ovarian cancer cell lines, and is also essential in cyclin E1 overexpressing cisplatin-resistant ovarian cancer cells." (PMID 32404140, 2020).
ovarian carcinoma (continued). "The same study showed that modification of ER stress by agents could enhance the cytotoxic activity of VCP inhibitors in treating ovarian cancer." (PMID 35841038, 2022). "In this study, our primary objective was to identify a clinically relevant agent that could enhance the cytotoxic effect of VCP inhibitors by modulating the unfolded protein response in ovarian cancer cells." (PMID 35740614, 2022). "Given that VCP has also been shown to be an essential gene in CCNE1 amplified ovarian cancer cells, future studies could analyze if CB-5083 and mifepristone combination display enhanced synergistic cytotoxicity in CCNE1 amplified ovarian cancer cells." (PMID 35740614, 2022). "A prior study found that VCP plays a crucial role in ovarian cancer cell survival through extraction and degradation of unfolded proteins in endoplasmic reticulum, and noted that lower expression of VCP was associated with poor response to platinum-based chemotherapy." (PMID 32404140, 2020). "Recent studies also identified VCP as a lineage-specific essential gene in ovarian cancer." (PMID 29367883, 2017). "The synergistic effects were also observed when CB-5083 was substituted with other VCP inhibitors DBeQ and NMS-873 suggesting that mifepristone enhances the cytotoxic effect of VCP inhibitors in ovarian cancer cells." (PMID 35740614, 2022). "In 2016–2017, some studies reported VCP/p97 and UPS as targets of vulnerability in ovarian cancer." (PMID 34576340, 2021). "VCP was identified as one of the necessary genes in 25 ovarian cancer cell lines, as well as 75 non-ovarian cell lines." (PMID 30587792, 2018).
sarcoma (11 papers, 2012 to 2024). A usually aggressive malignant neoplasm of the soft tissue or bone. "The identification of VCP as co-factor to AT3 strengthens the connection between ALS and fusion-associated sarcomas." (PMID 38326311, 2024). "Mutations in six genes can explain about 60–70% of fALS and about 10% of sALS cases: SOD1, TARDBP, FUS (fused in sarcoma), VCP (valosin-containing protein), OPTN (optineurin), and C9orf72." (PMID 32046060, 2020). "Here, we identify VCP as a co-factor to AT3, beginning with comparative proteomics of sarcomas from our mouse genetic model of ASPS as well as human cancer cell lines that natively express AT3." (PMID 38326311, 2024). "We first demonstrate reduced nuclear-to-cytoplasmic ratios of transactive response DNA-binding protein 43 (TDP-43), fused in sarcoma/translocated in liposarcoma (FUS) and splicing factor proline and glutamine rich (SFPQ) in VCP mutant motor neurons." (PMID 34396115, 2021).
hepatocellular carcinoma (10 papers, 2012 to 2025). A malignant tumor that arises from hepatocytes. "In hepatocellular and gastric carcinoma, the elevated expression of VCP is combined with increased incidence of recurrence, whereas the level of VCP in hepatocellular carcinoma tissues was negatively associated with the level of miR-129-5p 41–44." (PMID 26081366, 2015). "Here, we identified valosin-containing protein (VCP) as a key regulator of CD8+T cells suppression in hepatocellular carcinoma (HCC)." (PMID 39848960, 2025). "It is interesting to note that there is a tight interconnection between the different components, for instance, in hepatocellular carcinoma progression, P97/VCP differentially regulates IRE1alpha and ATF6 resulting in different outputs." (PMID 31671908, 2019). "VCP expression has also been correlated with cancers, including non-small cell lung carcinoma and hepatocellular carcinoma." (PMID 23755301, 2013). "Moreover, overexpression of NEAT1 inhibited the expression of miR-129-5p in hepatocellular carcinoma by regulating its targets, namely, valosin-containing protein (VCP) and inhibitor of kappa B (IκB)." (PMID 29147064, 2017). "Elevated expression of Valosin containing protein (VCP)/p97 in hepatocellular carcinoma (HCC) is correlated with increased incidence of recurrence." (PMID 24194897, 2013). "Moreover, elevated expression of VCP in hepatocellular carcinoma (HCC) is correlated with increased incidence of recurrence." (PMID 22536440, 2012).